HIF1A (hypoxia inducible factor 1 subunit alpha)
Diseases named in the same sentence as HIF1A in open-access papers (continued):
Sharing a sentence is not in itself a finding about the gene and the disease.
tumor (continued). "The expression of HIF‐1α was significantly higher in pT1b than in non‐neoplasia (p < 0.001) and in pT1b than in pTis‐T1a (p = 0.00472)." (PMID 37329213, 2023). "In null mice with subcutaneous xenograft tumors, silencing COMMD3 inhibited tumor development and expression of HIF1α, VEGF, and CD34." (PMID 36776284, 2023). "A murine HCC study reported that sublethal heating enabled tumor cells to acquire enhanced proliferative, invasive, and metastatic characteristics via the hypoxia/HIF-1α TGF-β/EMT axis." (PMID 36831664, 2023). "Third, NAC1 can promote glycolysis through its interaction with HIF-1a, and is critically required for the development, survival, and function of tumor cells." (PMID 37626718, 2023). "In the hypoxic microenvironment of the EOC, SENP1 alleviates tumor cells’ sensitivity to chemotherapy via deSUMOylating HIF-1α and upregulating its expression." (PMID 37415251, 2023). "Separately, lactic acid promotes angiogenesis via the HIF-1α/VEGF axis in the tumor microenvironment, contributing to tumor growth and the development of distant metastases." (PMID 37180129, 2023). "HIF-1α expression was originally identified in several cancer types and in metastases, suggesting a role for HIFs in tumor progression and worse outcome in patients." (PMID 37124241, 2023). "ANGPTL4 is a known angiogenic factor that can be directly induced by HIF-1α in tumor cells under hypoxic conditions, and its expression is significantly increased in BC patients." (PMID 37138324, 2023). "As a well-known core molecule of tumor angiogenesis potential, HIF-1α was also detected by WB analyses and IHC staining." (PMID 36647454, 2023). "This led to the accumulation of HIF-1α in endothelial cells, which promoted angiogenesis and permeability, as well as tumor migration." (PMID 37122754, 2023). "Chen and colleagues noted that photosan-mediated PDT and HIF1α siRNA nanocomposite resulted in a significant 40% reduction in tumor volume after 10 days of treatment." (PMID 36768975, 2023). "A hypoxic TME triggers the increased expression of HIF1α in tumor cells and MDSCs, which results in the upregulation of the PD-L1 and glycolytic pathways in both cells, while the high expression of HIF1α in TILs provokes PD-1 expression." (PMID 37111629, 2023). "The accumulation of HIF1α promotes the induction of several gene targets, such as leptin and ObRs, in adipocytes, fibroblast and tumor cells." (PMID 37686525, 2023). "In CDKN2A-null mouse melanocytes, AKT cooperates with HIF-1α to induce in vitro melanocyte transformation and in vivo tumor growth." (PMID 36901857, 2023). "Ldha is associated with the HIF-1 signaling pathway, and it has been documented that knockdown of HIF-1α enhances the tumor-killing capacity of NK cells and upregulates expression levels of IFN-γ, granzyme B, and Cd107a in splenic NK cells." (PMID 37039643, 2023). "During normoxic conditions, HIF-1α levels are kept low by the Von Hippel-Lindau (VHL) tumor suppressor which targets HIF-1α for ubiquitin-mediated proteasomal degradation." (PMID 37187740, 2023). "Increased rates of HIF-1α synthesis in colon, gastric, lung, skin, ovarian, pancreatic and prostate gland carcinomas have been shown to correlate with tumor proliferation rates, malignancy grade and therapy resistance, and, ultimately, with adverse outcomes." (PMID 37542119, 2023). "Increased lactate concentrations further stabilize hypoxia-inducible factor (HIF)-1α, thereby driving a tumor-promoting phenotype in bone marrow-derived, tumor-educated TAMs, characterized by enhanced expression of arginase and VEGF." (PMID 36845555, 2023). "Tumor development and maintenance are aided by NF-κB, while cellular proliferation and adaptability to angiogenic signals are aided by HIF-1α." (PMID 36891273, 2023). "In murine MM models, inhibiting HIF‐1α downregulated pro‐angiogenic genes, including vascular endothelial growth factor, and led to a reduction in the weight and volume of the tumor burden." (PMID 37840445, 2023).
tumor (continued). "The released siRNA and pASO efficiently inhibited the expression of HIF-1α and Bcl-2 under irradiation and potently inhibit tumor growth." (PMID 37242692, 2023). "CA9 is regulated by the transcription factor hypoxia‐inducible factor‐1α (HIF‐1α), which can regulate the pH value inside and outside of tumor cells and indicate the progression of malignant tumors." (PMID 36537608, 2023). "Considering the important role of HIF-1α in angiogenesis, we next investigated the effect of GSTZ1 on HIF-1α expression, tumor progression, and metastasis in orthotopic mouse models of HCC." (PMID 37906252, 2023). "Numerous reports have revealed that copper ions have a close relationship with tumor angiogenesis, which was dependent on the interaction between copper and hypoxia inducible factor 1 subunit alpha(HIF-1α)-related signaling pathways." (PMID 36882769, 2023). "Recent studies reveal allopurinol suppresses the expression of HIF-1α in cancer cells and HUVECs, and also inhibits tumor growth detected by xenograft and PDX models." (PMID 37752569, 2023). "Our data indicate that the suppression of HIF-1α activity and the impairment of tumour cell-induced angiogenesis is mediated through the inhibition of HIF-1α translocation into the nucleus." (PMID 37446252, 2023). "The protein expression of angiogenesis-related genes such as CCNE1, a disintegrin and metalloprotease 17 (ADAM17), mevalonate diphosphate decarboxylase (MVD), SMA_MVD, VEGFA, VEGFB, VGFR2, HIF-1α in tumor tissues was explored." (PMID 36959862, 2023). "It has been shown that targeting HIF-1α can eliminate PD-L1-mediated immune escape in the tumor microenvironment and increase immune tolerance in normal tissues." (PMID 37240068, 2023). "Hypoxia is a common feature of the tumor microenvironment, under which the mitochondria of tumor cells regulate the balance of ROS, leading to HIF-1α accumulation, activating protective autophagy and promoting tumor cell survival." (PMID 36678567, 2023). "HIF2α is believed to have a pro-tumorigenic role in ccRCC, while HIF1α inhibits aggressive tumor behavior, thereby acting as a tumor suppressor." (PMID 37190141, 2023). "An anti-tumor effect was mediated via the suppression of HIF-1α, while the others were anti-inflammatory and anti-fibrotic effects, such as the downregulation of NF-κB, IL-6, and TGF-β." (PMID 37511305, 2023). "HIF-1a is a determinant of aerobic glycolysis in tumor cells and is crucial in glucose metabolism, proliferation, and invasion in cancer." (PMID 37036874, 2023). "As a master transcription factor, HIF-1α is situated at the convergence of multiple oncogenic and tumor suppressor pathways, including MAPK/ERK pathways." (PMID 37709757, 2023). "We then investigated the in vivo effects of HIF-1α inhibition combined with PA + LC treatment on tumor xenograft growth." (PMID 38066600, 2023). "In head and neck cancer (HNSC), hypoxia-induced HIF-1α overexpression promotes tumor migration and invasion via morphologic transition, matrix metalloproteinase (MMP) activity, and nuclear deformation." (PMID 37095487, 2023). "After 1 week of treatment, DCE-MRI imaging demonstrated a reduction in tumor blood flow and permeability, indicating effective suppression of HIF-1α expression in late-stage solid tumors." (PMID 37711747, 2023). "To confirm that tumor neutrophils indeed exhibited a pronounced glycolytic signature as well as enhanced HIF-1α expression, we assessed the protein expression of glucose transporter 1 (GLUT1; a glycolytic marker) and HIF-1α by immunofluorescence." (PMID 36614196, 2023). "STK11 is also a central regulator of tumor metabolism through the regulation of HIF-1α-dependent metabolic reprogramming." (PMID 37351538, 2023). "In response to hypoxia, tumor cells stimulate transcription factor HIF-1a production, which upregulates the synthesis of VEGF." (PMID 36765912, 2023).
tumor (continued). "Immunoblots depicting expression of IMS-Prdx5 in the HCT116 tumor lysates similarly demonstrated that the antioxidant enzyme significantly decreases HIF-1α stabilization and transcriptional activity." (PMID 36935009, 2023). "HIF-1α can interact with other inflammatory protein complexes, carrying out a crucial role in tumor inflammation’s regulation." (PMID 37445908, 2023). "It has been shown that in order to adapt to a hypoxic environment, tumor cells express a high level of HIF-1α, which stimulates cell metabolism and proliferation." (PMID 36937390, 2023). "Upregulated THBS2 expression in CRC cells inhibits anti-tumour immunity through the HIF1A/lactic acid/GPR132 pathway." (PMID 37884956, 2023). "For example, the pivotal role of hypoxia-inducible factor-1α (HIF-1α) in tumor development has been identified, where HIF-1α triggers the expression of HK II by binding to its promoter." (PMID 38202657, 2023). "LOX acts on VEGF induction and HIF1α activation, and promotes tumor progression and metastasis, including OS." (PMID 37240338, 2023). "Hypoxic cells that form the core of the tumor mass are under the control of hypoxia-inducible factor -1α (HIF-1α)." (PMID 36891273, 2023). "Administration of melatonin has been shown to decrease the HIF1α protein level inside the tumor mass and prevented the growth of tumors in mice." (PMID 37605723, 2023). "The L169P VHL variant is comparable to WT VHL in terms of protein stability, ability to degrade HIF1α factors and ability to regulate hypoxia gene expression, as well as in the suppression of ccRCC tumor cell growth." (PMID 37762376, 2023). "In vivo investigations have reported that targeting HIF-1α remarkably inhibits tumor vascularization." (PMID 36891273, 2023). "Strategies to alleviate hypoxia and inhibit HIF-1α in the tumor microenvironment are an important way to treat tumors." (PMID 37670948, 2023). "Through repression of the NOX1/VEGF axis and activation of mTOR and HIF1-α, STK11 loss triggers tumor vascularization." (PMID 37370686, 2023). "Studies over the past decade have emphasized HIF-1α as the central regulator of tumor cell survival, proliferation, angiogenesis, and metastasis under graded oxygen tension." (PMID 36891273, 2023). "Inhibit HIF-1α protein expression and decrease growth of tumor xenografts.Inhibit viral RNA synthesis." (PMID 37600803, 2023). "In cancer cells, the HIF-1α is overexpressed, which regulates tumor survival-related genes, such as CXCL12 and CXCR4." (PMID 36207479, 2023). "Among the main factors that can induce such metabolic changes are TGF-β ligands released by tumor cells and the activation of HIF-1α." (PMID 37174079, 2023). "analyze changes of HIF-1α tissue amount with respect to tumor nuclear grade (G) and tumor-node-metastasis (TNM) stage, 3)." (PMID 38273861, 2023). "HIF-1α is a transcription factor that regulates numerous cellular pathways involved in tumor progression, such as glycolytic metabolism, metastasis, and angiogenesis." (PMID 36831463, 2023). "It has also been shown that mROS can stabilize HIF1α protein and activate HIF1α signaling, leading to the tumor’s malignant progression." (PMID 37644092, 2023). "HIF1α, a major regulatory factor that promotes angiogenesis, is abnormally high expressed in a variety of tumors and is closely related to tumor metastasis." (PMID 37644092, 2023). "The HIF-α isoforms HIF-1α and HIF-2α exert opposing effects on ccRCC progression with HIF-1α acting as a tumor suppressor whereas HIF-2α exerts pro-oncogenic potential." (PMID 36831657, 2023). "Currently, there are studies reporting that HIF-1α inhibitors are a promising method to enhance anti-tumor immunity and can synergize with anti-PD-1 to inhibit tumor growth in vivo." (PMID 37341987, 2023).
tumor (continued). "Of these miRNA molecules, miR-18a stood out, as upon its overexpression, they observed a tumour growth decrement and tumour metastasis suppression, in part through the direct regulation of hypoxia-inducible factor 1α (HIF1A) activity." (PMID 36831192, 2023). "Of note, we observed a decreased presence of HIF1A+ tumor cells in 6-thio-dG-treated mice with respect to LLC control mice." (PMID 37085672, 2023). "Under persistent hypoxia, HIF-1α/IL-1β loop between tumor cells and TAMs fosters epithelial-mesenchymal transition (EMT) and immune evasion." (PMID 36845131, 2023). "Accordingly, loss of complex III function during hypoxia leads to decreases in ROS signaling, decreases in hypoxic HIF-1α stabilization and decreases in tumor cell growth in vitro and in vivo." (PMID 36935009, 2023). "In this vector, IL-12 secretion was restricted to hypoxic microenvironments within the tumor site by fusion of IL-12 with the oxygen degradation domain (ODD) of HIF1α." (PMID 37663131, 2023). "Relative vessels number, necrosis areas and Ki-67 index were assessed microscopically; tumor volumes were determined by 3D reconstruction from histological images; serum levels of HIF-1α, IL-1β, and TNFα were determined by ELISA." (PMID 37542119, 2023). "The additional pathogenic mechanism is Lysine-specific demethylase 1 (LSD1) that stabilizes hypoxia-inducible factor 1α (HIF1α) to promote tumor progression." (PMID 36980957, 2023). "Compared to those in the control group, the enhanced tumor progression was suppressed and the volume of primary tumors was significantly decreased to the same degree in the HIF-1α-i and AsA ( +) groups." (PMID 38012636, 2023). "At the initial stage, when resources are sufficient, T cells use glucose for glycolysis and mitochondrial metabolism to generate T cells with tumour-killing effects, which involves the activation of HIF-1α and/or Myc." (PMID 37108242, 2023). "As expected, the level of PYCR1 pY135 and IGF1R phosphorylation were significantly correlated; the signals of PYCR1 pY135 also exhibited a positive relationship with that of HIF-1α in distinct tumor regions." (PMID 37777542, 2023). "In the hypoxic environment of the tumour, HIF‐1α/HIF‐2α cannot be hydroxylated due to inactivation of PHDs." (PMID 36478328, 2023). "HIF-1α also induces the overexpression of glucose transporters to maintain tumor energy production and proangiogenic factors, including vascular endothelial growth factor (VEGF), to stimulate the development of new blood vessels." (PMID 38140111, 2023). "Now, a question still remains: how does tumor cell survival, proliferation, angiogenesis, and metastasis occur in the truancy of HIF-1α." (PMID 36891273, 2023). "HIF-1α expression was available in all 29 cases and showed mainly cytoplasmic postivity in tumor cells (median 0%; range 0% to 40%)." (PMID 37958373, 2023). "HIF-1a is a determinant of aerobic glycolysis in tumor cells, and hypoxia increases the expression of HIF-1a." (PMID 37036874, 2023). "HIF-1α, a key transcription factor induced by tissue hypoxia, regulates the transcription of genes involved in angiogenesis, cell survival, and tumor cell invasion." (PMID 36982254, 2023). "Taken together, these results confirm that IGFL2‐AS1 can maintain CRC tumor growth through the HIF‐1α/CA9 pathway in vivo." (PMID 36537608, 2023). "One of the major mechanisms whereby tumor cells mediate hypoxic responses involves the upregulation of HIF-1α, which affects metabolic reprogramming." (PMID 37864196, 2023). "For instance, in breast cancer cells, it has been verified that Parkin acts as a tumor suppressor via ubiquitinating HIF-1α on Lys-477 site." (PMID 37190313, 2023). "Its mechanism of action includes promoting tumor angiogenesis by affecting HIF-1α activity and regulating the secretion of various angiogenic factors." (PMID 37427098, 2023). "HIF-1α is the most important transcription factor regulating CD73 expression in the tumor microenvironment." (PMID 37481646, 2023).
tumor (continued). "HIF-1α promotes tumour neoangiogenesis as well as aerobic glycolysis by LDH-A and pyruvate dehydrogenase kinase 1 (PDK1) expression." (PMID 36928373, 2023). "For example, pro-tumorigenic CAFs upregulate nitric oxide synthases (NOS)-1 with nuclear factor erythroid 2-related factor 2 (NRF2 and HIF1A in the tumor microenvironment." (PMID 36831498, 2023). "Previous studies have shown that UBE2S can regulate tumor development through the VHL/HIF‐1α signaling pathway." (PMID 37563971, 2023). "Recently, TRAF6 has been reported to contribute to tumor angiogenesis by up-regulating HIF-1α expression." (PMID 36678795, 2023). "Prior to YC-1 with PA + LC treatment, the anti-tumor effects of PA + LC was assessed in HIF-1α KD and SC HepG2 cell tumors." (PMID 38066600, 2023). "In our study, the high HRI score group consistently possessed a higher HIF1A expression level than the low-risk counterpart, indicating the effectiveness of the HRI score to reflect hypoxia exposure in CC tumor tissues." (PMID 36925652, 2023). "During rapid tumor cell multiplication in patients with non-small cell lung cancer, tumor cells are in a relatively hypoxic state, making HIF-1α more likely to be activated and stay in a highly expressed stage." (PMID 37065830, 2023). "To summarize, chromium appears to induce carcinogenic processes by inhibiting the tumor suppressor miR-143, leading to activation of proangiogenic mediators such as HIF1-α and IL-6." (PMID 37593220, 2023). "HIF-1α has been found to be overexpressed in many cancers, and a variety of deubiquitination enzymes act as oncogenes to increase tumor development through the stabilization of HIF-1α." (PMID 37190313, 2023). "However, TACE embolization can cause tumor tissue ischemia and hypoxia, leading to upregulation of hypoxia-inducible factor-1 alpha (HIF-1α) and subsequent upregulation of levels of VEGF, FGF, and other factors, which may contribute to tumor recurrence and metastasis." (PMID 37880661, 2023). "Experiments in vitro verified that rhIL-37 reduced IL-6, pSTAT3Y705, cyclin D1, and HIF-1α levels that contributed to tumor cells proliferation and migration, and Bcl-2 level that inhibited apoptosis in A498 and Caki-1 cells." (PMID 37928545, 2023). "Concurrently, with the recognition of the pivotal role of HIF-1α in tumor adaptation, there is a growing landscape of cancer therapies targeting HIF-1α." (PMID 38140111, 2023). "Other than hypoxia, many genetic alterations inactivating tumor suppressors or activating oncoproteins have been reported to increase the basal levels of HIF-1α in cancers and contribute to tumor progression and angiogenesis." (PMID 36900356, 2023). "An examination of core and invasive edges of invasive ductal breast carcinoma showed that tumor edges are characterized by increased staining of HIF-1α, CA9, and GLUT1." (PMID 37490147, 2023). "Some of the proteins with elevated expression in TSC2‐ cells have previously been linked to mTORC1‐driven tumours in TSC, including HIF‐1α, MMPs, VE‐cadherin, IL‐6 and VEGF." (PMID 37337371, 2023). "Hypoxia-inducible factor-1α (HIF-1α) is overexpressed in hypoxic conditions and its expression correlates with tumor cell growth, lymph node metastasis, and poor clinical outcome." (PMID 37594996, 2023). "Being a crucial transcription factor accountable for the cells and tissues adaptation to hypoxia, HIF-1α also helps tumor cells survive and progress in the hypoxic microenvironment through transcriptional activation of over 100 downstream genes." (PMID 36747531, 2023). "RAGE knockdown and KRAS signaling inhibition can promote HIF1α degradation and increase hypoxia-induced tumor cell death." (PMID 37701037, 2023). "In the presence of hypoxic stress, tumor cells initiate the transcription and secretion of hypoxia-inducible factor 1 alpha (HIF-1α)." (PMID 38057843, 2023).